ERG28 (ergosterol biosynthesis 28 homolog)
Synonyms: C14orf1; NET51
Tractability: Antibody: UniProt predicts a signal peptide or a membrane-spanning region. PROTAC: ubiquitination databases record sites on it.
Gene: Protein-coding gene on chromosome 14 (75,649,791 to 75,661,570, reverse strand). Ensembl gene ENSG00000133935.
Subcellular location: Endoplasmic reticulum membrane
Gene Ontology:
Molecular function: identical protein binding; protein binding
Cellular component: transport vesicle; membrane; endoplasmic reticulum membrane
Genetic constraint (gnomAD): Loss-of-function variants: 9 observed, 16.52 expected, observed/expected ratio (o/e) 0.54, 90% interval 0.33 to 0.95. The upper end of that interval is the gene's LOEUF score, 0.95, which puts it in group 4 of 6, group 1 being the genes least tolerant of losing a copy. Missense variants: 117 observed, 182.85 expected, observed/expected ratio (o/e) 0.64, 90% interval 0.55 to 0.75. Synonymous variants: 61 observed, 72.43 expected, observed/expected ratio (o/e) 0.84, 90% interval 0.68 to 1.04.
Homologues: Orthologues: chimpanzee ERG28 (100% identical), macaque ERG28 (100% identical), rabbit ERG28 (99% identical), mouse Erg28 (98% identical), rat Erg28 (98% identical), guinea pig ERG28 (97% identical), pig ERG28 (91% identical), tropical clawed frog erg28 (76% identical), zebrafish ERG28 (75% identical), dog ERG28 (62% identical).
Diseases named in the same sentence as ERG28 in open-access papers:
ERG28 is named in the same sentence as 1 disease in open-access papers, as found by Europe PMC text mining. Sharing a sentence is not in itself a finding about the gene and the disease.
ERG28 shares sentences with these, for which no sentence is quoted: prostate carcinoma (1 paper).